SLC14A1 (solute carrier family 14 member 1 (Kidd blood group))
Diseases named in the same sentence as SLC14A1 in open-access papers (continued):
Sharing a sentence is not in itself a finding about the gene and the disease.
tumor (20 papers, 2016 to 2026). "Further investigation is needed to substantiate this finding and determine whether the Slc14a1 gene rearrangement is associated with tumor cell invasion, metastatic spread, aggressiveness, tumor progression, recurrence and clinical outcomes." (PMID 32703295, 2020). "Fib-BMP5 was found mainly in the tumour samples, and was characterized by the elevated expression of SLC14A1, NRG1, and WNT5A." (PMID 41281745, 2025). "We initiated an investigation to understand the dysregulation of SLC14A1 expression levels within CRC tumor tissues." (PMID 39061061, 2024). "Regarding the relationship between SLC14A1 and other tumor types, several studies have indicated its potential distinctive function in specific cancer forms." (PMID 39061061, 2024). "In parallel, either STAT1 knockdown in CAFs or cGAS/STING knockout in cancer cells significantly repressed tumor growth and SLC14A1+CAF formation in vivo, concomitantly enhancing the chemotherapy sensitivity." (PMID 37079123, 2023). "Further research is therefore required to accurately analyze the effects of SLC14A1 gene expression on each aspect of tumor progression (including proliferation, invasion, angiogenesis, and metastasis) to guide novel therapeutic strategies." (PMID 36934247, 2023). "When tested in a xenograft model, introduction of SLC14A1+ CAFs into the tumor increased tumor growth." (PMID 37569686, 2023). "The average tumor size of xenografts from SLC14A-NLS- was similar to that of SLC14A1-overexpressing UMUC3 cells and much smaller than that of the mock (P < 0.01)." (PMID 33052246, 2020). "In the UTUC (n = 42) and UBUC (n = 36) subsets, SLC14A1 mRNA levels were downregulated in tumor specimens compared to their normal counterparts." (PMID 33052246, 2020). "Total and membranous SLC14A1 played tumor suppressive roles through the inhibition of cell proliferation and metastasis in distinct UC-derived cells and animal models." (PMID 33052246, 2020). "In this study, we uncovered that the nuclear as well as membranous SLC14A1 proteins play tumor suppressive roles through several signaling pathways in UC in clinical specimens, in vitro and in vivo." (PMID 33052246, 2020). "Moreover, suppression of SLC14A1+ CAF development through STAT1 or STING inhibition enhances tumor cell vulnerability to chemotherapeutic agents." (PMID 41301792, 2025). "In different types of human tumors, Slc14A1 has been described as a tumor suppressor 62-64." (PMID 38356711, 2024). "Hence, a series of in vitro and animal model experiments suggested that SLC14A1 protein, particularly the membranous form, plays a tumor suppressive role in UC." (PMID 33052246, 2020). "Accordingly, followed by suppression of DEGS1 transcription and translation, SLC14A1 may also inhibit tumor growth/cell proliferation in UC-derived cells through hindering lipotoxicity." (PMID 33052246, 2020). "In addition, UT-B suppresses tumor growth; overexpression of UT-B inhibits colony formation of lung cancer cell lines transfected with the SLC14A1 genes." (PMID 28503151, 2017). "Thus, SLC14A1 plays a clinical role as a tumor suppressor in UCs." (PMID 33052246, 2020). "Our results revealed that, compared to para-cancerous tissues, the expression levels of SLC14A1, NEFH, MSMB, KRT23, and KRT15 were significantly downregulated in PCa tumor tissues, while ARHGEF38 expression was notably upregulated, consistent with our initial predictions." (PMID 40260298, 2025). "Pathway analysis suggested that chemotaxis and integrin- and cadherin-mediated cell adhesion were the most functionally relevant processes (GeneGo Metacore), with two genes present in every sample type comparison (e.g. benign vs. tumor) across all studies - FLRT3 and SLC14A1." (PMID 27732966, 2016).
tumor (continued). "In mouse xenograft experiments, the average tumor size at day 14 after transplantation was smaller in SLC14A1-overexpressing UMUC3 cells than in the mock (P < 0.05), while it was restored to the similar size as the mock in xenografts from SLC14A1(C25S/C30S)-overexpressing cells." (PMID 33052246, 2020).
cancer (13 papers, 2012 to 2025). A tumor composed of atypical neoplastic, often pleomorphic cells that invade other tissues. "Solute carrier family 14 member 1 (SLC14A1), a urea transporter highly expressed in CAFs, remodels cell adhesion mechanisms, thereby promoting cancer stemness and chemoresistance." (PMID 41275427, 2025). "Our GSEA analyses suggest that SLC14A1 is intricately woven with the threads of TGF-β signaling and EMT, two pivotal elements notoriously implicated in cancer metastasis." (PMID 39061061, 2024). "When taking the expression of SLC14A1 in different cancer types and their related para-cencerous tissue into consideration." (PMID 36257969, 2022). "Although the SLC14A1 protein was frequently lowly expressed in several and advanced cancers, this is the first study to identify that epigenetic silencing contributes to its low transcription and subsequent low translation." (PMID 33052246, 2020). "It enhances cancer cell stemness and chemoresistance by up‐regulating SLC14A1+ CAFs." (PMID 41275427, 2025). "However, SLC14A1’s role in cancers, particularly CRC, is yet enigmatic, necessitating comprehensive investigations to unravel its functional and mechanistic implications." (PMID 39061061, 2024). "Thus, our model predicts that induction of SLC14A1 expression, combined with arginine depletion may kill cancer cells." (PMID 32103057, 2020). "SLC14A1 and TEK, underexpressed in the stage IV cancer (log2(FC) = -1.06, FDR = 0.0007; log2(FC) = -1.09, FDR = 9.26e-06), were two genes only regulated by GATA1." (PMID 25648588, 2014). "In such a context, chemotherapy treatment, which could trigger cancer DNA double-strand breaks, activated the cGAS-STING pathway and subsequently induced more SLC14A1+CAF formation." (PMID 37079123, 2023).
neurodegenerative disease (2 papers, 2023). A disorder of the central nervous system characterized by gradual and progressive loss of neural tissue and neurologic function. "Although the precise role of the Slc14a1 gene in neurodegenerative diseases remains poorly understood, several studies have reported the dysregulation of Slc14a1 expression in neurodegenerative diseases, including AD, HD and ALS." (PMID 37410787, 2023).
neurological diseases (2 papers, 2023). "Although studies of UT-B transporters in neurological diseases are lacking, our group has previously identified increased expression of Slc14a1 in a transgenic sheep model of HD." (PMID 37520429, 2023).
blood cancer (1 paper, 2017). "In our results, SLC14A1 high expression correlated with low IC50 values in blood cancer cell lines and acted as a good prognostic predictor in AML patients for both GSE12417 and TCGA CN-AML datasets." (PMID 27903973, 2017).
SLC14A1 also shares sentences with these, for which no sentence is quoted: bladder tumors (3 papers); bladder urothelial carcinoma (2); acute renal failure (1); anemia (1); breast carcinoma (1); carcinoid (1); COVID-19 (1); gastric cancer (1); hydrops fetalis (1); lung squamous cell carcinoma (1); metastatic prostate carcinoma (1); muscular dystrophy (1); non-small cell lung carcinoma (1); Obesity (1); parkinsonian disorder (1); Sickle Cell Anemia (1); uremia (1); Uterine leiomyoma (1).